Y_RNA (Y RNA )
Gene: Miscellaneous RNA gene on chromosome 5 (173,052,452 to 173,052,555, reverse strand). Ensembl gene ENSG00000207210.
Homologues: Orthologues: chimpanzee Y_RNA (97% identical), guinea pig Y_RNA (82% identical), guinea pig Y_RNA (81% identical). Paralogues in human: Y_RNA (80% identical), Y_RNA (79% identical), Y_RNA (78% identical), RNY1 (77% identical), Y_RNA (77% identical), RNY1P4 (76% identical), RNY1P5 (76% identical), Y_RNA (76% identical), RNY1P14 (75% identical), RNY1P7 (75% identical), Y_RNA (75% identical), RNY1P11 (74% identical), and 91 more.